S100A8 (S100 calcium binding protein A8)
Diseases named in the same sentence as S100A8 in open-access papers (continued):
Sharing a sentence is not in itself a finding about the gene and the disease.
tumor (continued). "The role of hsa-miR-185 in human BC has also been identified as a tumor suppressor since it inhibits BC by regulating S100A8/A9, NF-κB/Snail signaling pathway, and programmed cell death." (PMID 36768939, 2023). "By immunofluorescence microscopy, we validated the transcriptional phenotype of MF tumor-associated keratinocytes and showed that KRT6A+S100A8+ are specifically found in the epidermis of advanced MF samples but not in HC skin." (PMID 37669110, 2023). "Although these studies strongly indicate that S100a8/a9 elicit powerful anti-tumor responses, their functions in hematological malignancies remain poorly understood." (PMID 36810783, 2023). "Subsequent studies with a mouse model of multiple myeloma and mouse thoracic tumors confirmed the earlier findings that S100A8 and A9 drive MDSC differentiation and function and are associated with aggressive tumor progression." (PMID 36831371, 2023). "S100a8/a9 elicits powerful anti-tumor responses and induces cell death program or apoptosis, which appears to be independent of death receptors like the Receptor of Advanced Glycation Endproducts or Fas-associated with death domain protein." (PMID 36810783, 2023). "Accordingly, the target-specific imaging of S100A8/A9 can be used to visualize the tumor-immune interaction." (PMID 35741108, 2022). "Carboxylated N-glycans are expressed on RAGE, for example, on immune and tumor cells, which mediate S100A8/A9 and RAGE binding, promoting receptor-mediated signaling and pathogenesis." (PMID 36613714, 2022). "Our findings also provide insight into S100A8's important involvement in carcinogenesis and metastasis and a proposed mechanism through which S100A8 expression modulates tumor immunology and metabolic activity." (PMID 35646116, 2022). "Consistent with the increased mRNA expression, elevated S100a8/S100a9 protein levels were also observed in MT mammary epithelial cell lines (G600), mammary tissues, and tumor tissues, as revealed by western blot analysis." (PMID 35304461, 2022). "Studies have shown that S100A8 expression is gradually increased in normal stroma, tumor center stroma, and the tumor invasive front stroma, suggesting that S100A8 is involved in the regulation of EMT in CRC." (PMID 35936690, 2022). "Tumor-infiltrating monocytes/macrophages increase tumor invasion and migration by increasing the expression of S100A8 and S100A9 in cancer cells." (PMID 35646116, 2022). "Recruited at the hypoxic tumor sites, CD11b+Gr1+ MDSCs produce S100A8, an alarmin not only involved in the recruitment of additional MDSCs, but also implicated in the activation of endothelial cells." (PMID 35309358, 2022). "This study provided more information about S100A8's latent involvement in tumor immunology and its potential application as a cancer biomarker." (PMID 35646116, 2022). "S100A8/A9 expresses in both the tumor microenvironment and the external environment and can be classified as a signal during the tumorigenesis." (PMID 36699089, 2022). "Infiltrating macrophages can upregulate S100A8 expression in tumor cells and promote their invasion and migration." (PMID 35111225, 2022). "In contrast to the presumed specificity of S100B, a variety of tumours and cells originating from all germ layers can be induced to express S100 proteins, particularly S100A8, S100A9, S100A12 and S100B, as a result of oxidative stress and tissue inflammation." (PMID 35323240, 2022). "SAA3 protein produced in response to S100A8 in the lungs also attracts and recruits circulating tumor cells to the niche and stimulates the production of inflammatory cytokines, such as TNFα, which promote tumor growth." (PMID 36497411, 2022). "Tumor cell migration and invasion are facilitated by the upregulation of matrix metalloproteinase expression and inhibited by the downregulation of S100A8 or S100A9, which correlates with their abnormal expression in many cancer types." (PMID 35783639, 2022).
tumor (continued). "S100A8/9 are small molecular calcium-binding proteins expressed on MDSCs and involved in tumor progression." (PMID 35585567, 2022). "Administration of anti-S100A8 neutralizing antibodies also suppresses tumor progression by the suppression of MDSC recruitments." (PMID 35780158, 2022). "The pro-inflammatory S100A8/9 heterodimer carried by MDSCs-Exos is chemotactic for MDSCs and plays the primary role in promoting the aggregation of MDSCs to the tumor tissue and pre-metastatic niche." (PMID 35154134, 2022). "Silva and colleagues discovered that S100A8 or A9 regulated tumor cell migration and invasion by upregulating the expression of matrix metalloproteinases." (PMID 35936690, 2022). "Among the upregulated DEPs, S100A8 is highly overexpressed in multifarious tumors and can promote the initiation and progression of cancers by regulating tumor cell movement, proliferation, differentiation, apoptosis and drug resistance." (PMID 35371990, 2022). "In fact, MDSCs-shed Exos contain proinflammatory mediators such as S100A9 and S100A8, which promote tumor progression and suppress anti-tumor responses." (PMID 35918733, 2022). "We also identified a novel double-negative T (DNT) cell population that was elevated in lungs of tumor-bearing mice treated with S100A8 for which the functional significance remains to be elucidated." (PMID 35655772, 2022). "For example, interleukin (IL)-6 and IL-8 released from myofibroblasts in the tumor microenvironment induce myeloid cells to differentiate into S100A8/S100A9-expressing myeloid-derived suppressor cells and M2 macrophages." (PMID 35177036, 2022). "Upregulation of S100A8/A9 occurs as a result of immune cells or the tumor itself infiltrating the tumor microenvironment, helping to create a pre-metastatic milieu." (PMID 35783639, 2022). "S100A8/A9 promotes tumor development and invasiveness by increasing leukemic cell growth through RAGE and secretion of pro-inflammatory cytokines through the TLR4-NFκB pathway." (PMID 35586193, 2022). "S100A8 is known to promote tumor proliferation and migration, and it even forms pre-metastatic niches." (PMID 33146829, 2021). "Single cell analysis of immune cells in GBM showed that S100A8/9 (macrophages markers) was highly expressed in immune cells in the tumor core, indicating that the infiltration of immune cells within the mesenchymal subtype." (PMID 33816228, 2021). "In tumor-bearing mice treated with mAbGB3.1 (10 ug/gm body weight), S100A8/A9 binding and signaling has been blocked and the accumulation of MDSCs in the peripheral blood and secondary lymphoid organs has been reduced." (PMID 34568077, 2021). "Research has shown that S100A8 is produced by tumor-infiltrated inflammatory cells that decorate the microenvironment and produce “pre-metastatic niches”, which benefit metastatic cell adhesion and growth." (PMID 34745098, 2021). "With S100A8/S100A9 as an important mediator in the TME, this study can pave the way for an imaging biomarker development for modern tumor therapy and ultimately underline its translational potential." (PMID 33401528, 2021). "Compared with para-cancer tissues, the expression levels of S100A4/S100A6/S100A10/S100A11/S100A13/S100A14/S100P were higher in HCC tissues, while the expression levels of S100A8/S100A9/S100A12 were decreased in tumor tissues." (PMID 33815482, 2021). "Effective extracellular S100A8/A9 concentrations for promoting apoptosis of tumor cells range from 20 to 250 μg/mL." (PMID 33567747, 2021). "Among the four clusters of dendritic cells, DC_C2_CD1C, DC_C3_LAMP3, and DC_C4_JCHAIN were derived from tumours, and DC_C1_FCER1A was derived from peripheral blood, which was assigned as monocyte-like DC because of the expression of monocyte marker S100A8." (PMID 33531485, 2021). "It has been found that although S100A8 was expressed at relatively low levels in the tumor cells, expression was 100-fold higher in the lung and liver, which are common sites of metastasis." (PMID 33567747, 2021).
tumor (continued). "There is a positive feedback mechanism between S100A8/A9 and several pro-inflammatory factors adding to tumor progression." (PMID 33567747, 2021). "MDSCs-secreted S100A8, which acts by destabilization of the tumor vasculature, represents a resistance-conferring factor induced by antiangiogenic therapies (AAT), which can be reverted by combining with ATRA through reduction of MDSCs levels." (PMID 35003065, 2021). "Evidence supporting that S100A8/A9 functions as a sign that attracts cancer cells to specific organs by tumor-derived factors locally and systemically, has proven beneficial in metastatic progression." (PMID 33567747, 2021). "When co-culturing lung tumor-derived M-MDSCs or G-MDSCs from mice with 4T1 breast carcinoma cells, tumor cell proliferation increased with augmented expression of S100A8/A9, Mmp8, Lyz2, Fpr, Ccl3, and Tgfb2." (PMID 34482371, 2021). "In murine metastatic lung tumor models, MDSCs were found to populate the tissue as early as 2 weeks prior to tumor formation; secrete IL-6, S100A8/A9, VEGF, and IL-10 in order to establish the tumor; and recruit additional MDSCs to the lung." (PMID 34482371, 2021). "S100a8 and S100a9 enhance the immunosuppressive activity of neutrophils and recruit immature myeloid cells to the tumor." (PMID 34070438, 2021). "The link between tumor infiltrating monocytes/macrophages and S100A8 and S100A9 expression in cancer cells supports their role in diffusion and spreading of cancer cells." (PMID 33801279, 2021). "In cancer, S100A8/A9 has been shown to have paradoxical functions by either promoting apoptosis or favoring tumor development, depending on the cellular context." (PMID 34360919, 2021). "Recently, S100A9 and S100A8 have been used to develop an attractive tool for the depletion of MDSCs in tumor-bearing mice." (PMID 34201758, 2021). "The expression of S100A8/A9 is closely related to tumor stage, lymph node metastasis and poor prognosis in NPC patients." (PMID 34568077, 2021). "In tumors, activation of the S100A8/A9/RAGE pathway has been shown to promote tumor progression in several types of cancer, including breast, prostate, and colorectal cancer, through the activation of the MAPK pathway and NF-kB." (PMID 34360919, 2021). "Five cell types, TIMP1+M3, S100A8+N3, TUBB+Mcyl, LAMP3+DC3, and TCL1A+pDC, all of which were enriched in MSC2, were positively associated with tumor progression (FDR < 0.05)." (PMID 34659209, 2021). "Further, STAT-3 has been identified as a crucial regulator of MDSC expansion that conveys the recruitment of MDSC to the tumor site by upregulating the pro-inflammatory S100A8 and S100A9 proteins." (PMID 33430105, 2021). "Positive correlation between PD-L1+ ICs and S100A8+ ICs can also be explained by the finding that tumor-infiltrating MDSCs show upregulated expression of PD-L1." (PMID 33146829, 2021). "It has been reported that tumor-infiltrating monocytes promoted invasion and migration of tumor cell via up-regulating S100A8 and S100A9 expression." (PMID 33758602, 2021). "Compared to non-tumor-bearing fatpads, mouse mammary epithelial cells and peritumoral stromal cells showed increased expression of both S100A8 and S100A9." (PMID 33446797, 2021). "S100A8/A9 heterodimer promotes tumor cell growth at low concentrations through RAGE signaling and NF-κB-dependent phosphorylation of p38 and p44/42 MAPKs in MCF-7 and MDA-MB231 cells." (PMID 33801279, 2021). "Evidence has shown that S100A8/9 is a significant participant in almost the entire course of MDSC activity in the tumor microenvironment." (PMID 34689842, 2021). "Screening for tumor-associated LMW protein and lipid changes in HNSCC tissue, here we identify S100A8, S100A9 and specific phospholipids to accumulate and lysophosphatidylcholine to be depleted in the tumor." (PMID 32733643, 2020).
tumor (continued). "Inhibition of S100A8 had the most pronounced effect on tumor-initiating sphere formation, reducing the number of spheres by more than 50 percent in all cell lines studied." (PMID 32503348, 2020). "RT-PCR analysis showed that the mRNA levels of Bv8, S100a8, S100a9, and Mmp9 were significantly higher in the lungs of tumor-bearing mice after 2 weeks of sunitinib treatment than those in tumor-bearing control mice." (PMID 32993785, 2020). "The xenografted cells multiplied in a time-dependent manner, and tumor volume and weight were observed to decrease after administration of S100A8 and S100A9." (PMID 32903598, 2020). "S100A8 and S100A9 have been implicated in inflammation and tumor development, exerting a complex and multifactorial role." (PMID 32733643, 2020). "Specifically, S100A8 transported by SEC23A inhibits metastatic colonization via autocrine activation of autophagy in extravasated tumor cells." (PMID 32811814, 2020). "Although a significant therapeutic benefit was observed, chemotactic redundancy (i.e., S100A8) was likely responsible for achieving only a modest reduction in tumor burden." (PMID 33123173, 2020). "In silico pathway analysis followed by candidate-based RNA interference mediated loss-of-function analysis revealed a critical role of S100A8, S100A9, and LGALS3BP as molecular determinants of TIC proliferation, migration, and in vivo tumor growth." (PMID 32503348, 2020). "In vivo, NOD/SCID mice injected with tumor cells with stable S100A8 interference developed significantly more extensive macroscopic lung metastases." (PMID 32811814, 2020). "The delay in tumor engraftment due to perturbation of S100A8 and S100A9 further corroborates our experimental findings and suggests a prominent role of these two proteins regarding cancer stemness in pancreatic TICs." (PMID 32503348, 2020). "Marking the same healthy stroma (ROI1) vs. tumor (ROI2) areas as for S100A8 and S100A9 analysis, lipid expression was displayed in a gel view format in the 400–1000 Da MW range." (PMID 32733643, 2020). "Previous studies demonstrated that MDSC induced by tumor-derived G-CSF express S100A8/A920,24, and that S100A8/A9 expression in the premetastatic tissue is indicative of the MDSC-mediated premetastatic niche." (PMID 32170086, 2020). "Extracellular S100A8/A9 from MDSCs and tumor cells stimulates macrophage polarization toward the tumor-promoting M2 phenotype, and this conversion switches off IL-12 production, which drives the development of NK cells and tumouricidal T lymphocytes." (PMID 30792719, 2019). "CXCL1/2 recruit CD11b(+)Gr1(+) myeloid cells into the tumor, which produce chemokines including S100A8/9 that enhance cancer cell survival, chemoresistance and metastasis." (PMID 31998654, 2019). "Proteomic studies in blood serum of patients with BC revealed Calprotectin–the heterodimer of the proteins S100A8 and S100A9 –as a tumour-associated protein that is linked to bladder wall muscle invasion of the tumour as well as cancer-specific survival." (PMID 30870488, 2019). "Extracellular S100A8/9, which is secreted via infiltrated immune cells or epithelial cells is involved in inflammatory-dependent tumor cell progression and development, therefore it can serve as a promising circulating biomarker for cancer diagnosis." (PMID 31528166, 2019). "More recent in vivo evidence showed that genetic deletion of the SLC27A2 gene (also known as FATP2) encoding the very long-chain acyl-CoA synthetase, specifically in neutrophils using the S100a8-cre mice, abrogated tumor growth in different tumor models." (PMID 31616408, 2019). "Serum protein levels and tumor transcript levels of S100A8 and S100A9 were used for detailed analysis to probe the role of these two proteins in GBM diagnosis and prognosis." (PMID 30808902, 2019). "A positive correlation was noted in the level of S100A8/9 in patients with a large tumor size (>2.5 cm) compared to a small tumor size (≤2.5 cm) (P<0.01)." (PMID 31528166, 2019).
tumor (continued). "MDSC exosomes polarize macrophages toward a tumor-promoting type 2 phenotype and possess S100A8/A9 chemotactic activity." (PMID 30792719, 2019). "S100A8/A9 is a heterodimer calcium-binding protein which is involved in tumor cell proliferation, adhesion and invasion, and is proposed as a biomarker for better diagnosis and prognosis in many cancers." (PMID 31528166, 2019). "No such relationship was observed for S100A9-positive monocytes, indicating a distinction between S100A8- and S100A9-expressing tumour-associated monocytes." (PMID 30558665, 2018). "Aberrant expression of S100A8 has been reported to be related to tumor progression in various cancer types." (PMID 30456203, 2018). "Various growth factors released from the primary tumor induce the expression of S100A8/A9 and creates a pro-inflammatory milieu, which facilitates the metastasis at the target site." (PMID 29568375, 2018). "While, several other studies have indicated that extracellular S100A8/S100A9 exhibits powerful anti-tumor responses by promoting cytotoxicity and apoptosis." (PMID 30558666, 2018). "In conclusion, CD11bhiF4/80low TAMs suppress CD8+ T-cell infiltration into tumor low hypoxic area of tumor tissue via secretion of S100a8/a9." (PMID 29991744, 2018). "We also assessed gene expression of various factors associated with the suppressive function of MDSCs including S100A8, S100A9, Nos3, Arg1 and Arg2 in BM-MDSCs compared to G-MDSCs from the tumor, spleen and lungs of tumor-bearing mice." (PMID 29677215, 2018). "The S100A8/A9 heterodimer has been shown to promote accumulation of myeloid-derived suppressor cells (MDSCs) in the primary tumor and their recruitment to premetastatic lungs." (PMID 29607329, 2018). "We found S100A8 to be expressed −7.75× less in EAC tumor cells compared to normal epithelial cells of the esophagus (P < 0.0001)." (PMID 29868478, 2018). "Once secreted in the extracellular space, S100A8/A9 act as chemo-attractants recruiting further inflammatory cells and creating an inflammatory microenvironment that promotes tumour development." (PMID 30558665, 2018). "The aim of this study was to examine how S100A8/A9 proteins mediate tumour-stroma crosstalk in PDAC." (PMID 30558665, 2018). "The protein heterodimer of S100A8 and S100A9 has been implicated in tumor development and progression." (PMID 29607329, 2018). "The S100A8 protein has been reported to promote tumor cell growth, to mediate endotoxin-induced cardiomyocyte dysfunction, to activate NK cells and to aggravate post-ischemic heart failure through the activation of RAGE-dependent signaling." (PMID 28637501, 2017). "Generally, high S100A8/A9 levels in tumor tissue or serum indicate a more rapid, aggressive course of disease 12, 13 in various human cancers." (PMID 28744322, 2017). "MDSCs are noted to secrete MMP9 to facilitate tumor invasion and metastasis and S100A8/9 to promote survival of cancer cells." (PMID 29142311, 2017). "Treatment with CCL2 blocking antibodies resulted in reduced S100A8/A9 expression and a significantly decreased number of pro-inflammatory monocytes in both spleen and lungs of 4T1.2-tumor bearing mice." (PMID 28744322, 2017). "In particular, it is reported that S100A1 and S100A7 are linked to tumor growth, while S100A4 and S100A8 are linked to metastasis." (PMID 28615627, 2017). "Many cellular and molecular components of the immunosuppressed tumor microenvironment have been identified as potential targets for treating advanced PCa, including MDSCs, NFκB, and pro-inflammatory protein S100A8/9." (PMID 29142311, 2017). "Several different cells including various tumor cells and immune cells have been reported as potential producers and providers of S100A8/A9 and this can also be found in the tumor microenvironment as well as in premetastatic tissue." (PMID 28744322, 2017). "As a paradigm for such future work, we suggest S100A8/A9 in vivo imaging as a first approach to non-invasively address tumor immune crosstalk." (PMID 28744322, 2017).